KIF18B (kinesin family member 18B)
Diseases named in the same sentence as KIF18B in open-access papers (continued):
Sharing a sentence is not in itself a finding about the gene and the disease.
cancer (24 papers, 2017 to 2026). A tumor composed of atypical neoplastic, often pleomorphic cells that invade other tissues. "Although an association between KIF18B and cancer has been reported, the role of this protein in tumorigenesis remains poorly understood." (PMID 33753726, 2021). "Based on survival curves, including OS, DFI, DSS, and PFI, KIF18B mRNA expression demonstrated reliable diagnostic value, indicating that KIF18B is a potentially promising biomarker for pan-cancer diagnosis." (PMID 34109209, 2021). "It was observed that mutations in KIF18B were predominant in cancer cases, notably in GBM." (PMID 40110038, 2025). "Additionally, the high expression of KIF18B was associated with unfavorable clinicopathological features and independently predicted poor prognosis in pan-cancer." (PMID 34109209, 2021). "The identification of cell cycle associated with many DEGs, including PLK1, ANLN and KIF18B/20A, across human cancers demonstrates that the most essential characteristic of cancer cells is sustained proliferation, and that this may lead to adverse survival outcomes." (PMID 38096046, 2024). "Kinesin family member 18B (KIF18B), a key protein in cell division and mitosis, has emerged as a potential diagnostic and therapeutic target in various cancers, including OS." (PMID 41977416, 2026). "This indicates that the oncogenic function of KIF18B in cancer cells is mediated through the collaborative engagement of diverse signaling pathways." (PMID 40110038, 2025). "Member of the driver protein family 18B (KIF18B) is a potential prognostic marker and is highly expressed in a variety of cancers." (PMID 40110038, 2025). "In summary, the overexpression pattern of KIF18B is TME-specific, suggesting the potential of KIF18B as a target for standardized cancer immunotherapy." (PMID 40110038, 2025). "As shown by our study as well as researches of other groups, KIF18B functions as an oncogenic protein in various types of cancer, thus developing KIF18B inhibitors would also be a promising anticancer strategy." (PMID 37957153, 2023). "For example, KIF18B expression significantly correlated negatively with the purity of stromal cells and immune cells in seven types of cancer." (PMID 35359374, 2022). "Coexpression analysis revealed that KIF11, KIF18B, KIF23, and MKI67 were positively associated with the expression of IQGAP3 in all cancer types presented in the heatmap." (PMID 36164370, 2022). "In recent years, studies have shown that KIF18B participates in the growth and development of a variety of cancers." (PMID 34109209, 2021). "Considering the potential prognostic value and biological function of KIF18B, it is essential to explore the fundamental mechanism of its dysregulation in pan-cancer." (PMID 34109209, 2021). "In summary, KIF18B was upregulated in pan-cancer tissues, compared with corresponding normal tissues." (PMID 34109209, 2021). "Per the KEGG analysis, KIF18B in pan-cancer tissues participated largely in antigen processing and presentation, cell cycle, cytosolic DNA sensing pathway, regulation of autophagy, and toll-like receptor signaling pathway." (PMID 34109209, 2021). "We extracted the mRNA levels of KIF18B from 33 cancer types in TCGA and plotted a box diagram of the expression of KIF18B in cancerous and adjacent tissues." (PMID 34109209, 2021). "Both KIF20A and KIF18B support mitosis and meiosis, as well as being potential biomarkers and molecular targets for cancer therapy." (PMID 34112092, 2021). "On the contrary, the overexpression of KIF18B promotes the proliferation, invasion, and migration of cancer cells." (PMID 32973873, 2020). "Kinesin family member 18B (KIF18B) has been identified as a potential oncogene involved in the development and metastasis of several cancer types." (PMID 32587775, 2020).
cancer (continued). "Furthermore, inhibiting KIF14 and KIF18B has been explored in other cancers, and future functional studies and drug sensitivity analyses will be essential to evaluate their potential as therapeutic targets." (PMID 40405535, 2025). "Overexpression of KIF18B is associated with poor cancer free survival and non-biochemical recurrence survival in PCa." (PMID 38049827, 2023). "Overexpression of KIF4A and KIF18B was observed in various cancers." (PMID 36499051, 2022). "To further evaluate whether KIF18B may have an immune-related role in cancer, we collected 47 common immune-related genes." (PMID 34109209, 2021). "TMB, MSI, MMRs, and DNA methylation correlated with KIF18B dysregulation in cancers." (PMID 34109209, 2021). "To further explore whether KIF18B could be used as a potential target for immune checkpoints in cancer, we examined the relationship between KIF18B expression and some known immune-related factors, displaying the outcome as a heat map." (PMID 34109209, 2021). "KIF18B reportedly functions as an oncogene in some human cancers, but the correlations between KIF18B and prognosis and immune-infiltrates in different cancers remain unclear." (PMID 34109209, 2021). "In our study, KIF18B expression correlated positively with the methylation and MMRs of most cancers, suggesting that DNA methylation and MMRs may change the expression of KIF18B." (PMID 34109209, 2021). "The expression of KIF18B mRNA in most cancers was different from that in normal tissues." (PMID 34109209, 2021). "In short, these correlations could indicate potential mechanisms and suggest that KIF18B plays a vital role in the recruitment and regulation of the immune system in pan-cancer." (PMID 34109209, 2021). "GSEA was used for the GO and KEGG analyses of KIF18B positively co-expressed genes in pan-cancers." (PMID 34109209, 2021). "Furthermore, we explored the basic biological function and molecular mechanisms that underpin the potential clinical value of KIF18B in pan-cancers." (PMID 34109209, 2021). "Yet, several studies have shown close connections between KIF18B and cancer." (PMID 32973873, 2020). "However, our findings provided new insights into the development and treatment of KIF18B in cancer." (PMID 34109209, 2021). "Therefore, we speculate that the high neo-antigen load causing the aberrant KIF18B expression and dysregulation in pan-cancer is a positive note for biomarkers of new antigens." (PMID 34109209, 2021). "The correlations of KIF18B with OS, DSS, DFI, and PFI in different cancers were visually observed." (PMID 34109209, 2021). "To assess whether KIF18B mRNA was expressed at different levels at various cancer stages, we extracted pathological stages, including stages I, II, III, and IV, from 33 tumors and integrated them with KIF18B mRNA levels." (PMID 34109209, 2021). "However, to date, the expression pattern, prognostic significance, and biological function of KIF18B in cancer have not been elucidated fully." (PMID 34109209, 2021). "KIF18B expression also correlated markedly negatively with infiltrating levels of T cells CD4 memory resting in eight types of cancer, macrophages M2 in six types of cancer, dendritic cells resting in six types of cancer, and mast cells resting in eight types of cancer." (PMID 34109209, 2021). "Moreover, KIF18B expression correlated considerably positively with infiltrating levels of T cells CD4 memory activated in nine types of cancer, T cells follicular helper in 12 types of cancer, macrophages M0 in eight types of cancer, and macrophages M1 in nine types of cancer." (PMID 34109209, 2021).
infection (1 paper, 2020). The state of being infected such as from the introduction of a foreign agent such as serum, vaccine, antigenic substance or organism. "Two shRNA lentiviral vectors specifically targeting KIF18B were constructed for infection of U2OS and HOS cells after viral packaging." (PMID 32587775, 2020).
KIF18B also shares sentences with these, for which no sentence is quoted: cutaneous melanoma (2 papers); bladder cancer (1); breast tumors (1); colon adenocarcinoma (1); colon cancer (1); diffuse large B-cell lymphoma (1); gallbladder cancer (1); lymphoid neoplasm (1); meningioma (1); oral cancer (1); prostate adenocarcinoma (1); rheumatoid arthritis (1).